IL17A (interleukin 17A)
Diseases named in the same sentence as IL17A in open-access papers (continued):
Sharing a sentence is not in itself a finding about the gene and the disease.
tumor (continued). "Studies using animal models of ETBF-associated carcinogenesis have revealed that BFT exacerbates tumor development by promoting the production of pro-inflammatory cytokines, including interleukin-17A (IL-17A) and CXCL1, in the MinApc+/− mouse model." (PMID 40650003, 2025). "Blocking both IL-17A and IL-10 can increase the tumor response to PD-1/PD-L1 inhibitor immunotherapy in patients with MSS mCRC." (PMID 41051603, 2025). "Studies showed that the combined use of anti-IL-17A antibody and gemcitabine can induce M1 polarization of macrophages and enhance anti-tumor response." (PMID 41384105, 2025). "Blocking the IL-17a signaling with neutralizing antibodies can inhibit the activity of TANs-stimulated tumor cells." (PMID 40568576, 2025). "Conversely, in aged OVX 67NR tumor-bearing mice, tacalcitol reduced Il17a expression, and calcitriol decreased Foxp3." (PMID 40894304, 2025). "Neutralising IL-17A reduced macrophage infiltration and tumour progression, confirming the role of Candida spp." (PMID 40278081, 2025). "Flow cytometry of tumours from ENO1‐vaccinated mice revealed a distinct immune infiltrate profile in KPC/IL17A−/− mice." (PMID 40831074, 2025). "Although stromal cell abundance was higher in IL17A+/+ tumours, gene expression patterns among inflammatory (iCAF), myofibroblastic (myCAF) and antigen‐presenting (apCAF) subtypes were similar between groups (data not shown)." (PMID 40831074, 2025). "Immunohistochemical staining showed that IL-17A+ cells were mainly distributed in the tumor tissue, while a few CD45 + immune cells were observed in the same area." (PMID 40486048, 2025). "This along with a greater CD4+ T‐cell interaction with B cells in IL17A−/− tumours suggests an enhanced humoral response and B‐cell activation." (PMID 40831074, 2025). "IL-17A and IL-33 levels declined progressively with tumor dedifferentiation and increased invasion depth, indicating immune suppression in advanced stages." (PMID 40725273, 2025). "Subsequently, the Tc17-derived IL-17A and IL-26 further promoted tumor progression, as validated by CCK-8, wound-healing, and transwell assays." (PMID 41516201, 2025). "An ANOVA was performed to assess the variation in the mean IL-17A concentration based on the type of tumor infiltration (lymphovascular invasion, muscular invasion, organ metastasis, serous invasion, submucosal invasion)." (PMID 40725273, 2025). "IL-17A subsequently recruits circulating neutrophils to the tumor site via CXC chemokines produced by epithelial cells, transforming these neutrophils into immunosuppressive cells." (PMID 40558272, 2025). "Tumor grade also had a significant influence on IL-17A expression, with higher IL-17A observed in lower-grade tumors (G1) and a marked decline across G2 to G3, as visually represented by the distinct curves for each grade in the interaction plot." (PMID 40725273, 2025). "MDSC development involves tumor-driven signals and inflammatory cytokines such as IL-17A, TNF-α, and G-CSF." (PMID 40918141, 2025). "Here, we explore the effect of combining IL17A depletion with a cancer vaccine to enhance anti‐tumour immunity." (PMID 40831074, 2025). "We detected that IL-17A increase was induced by tumor and CUMS, which was reversed by HIS treatment." (PMID 39720595, 2024). "In the lungs, IL‐17A can induce the production of IL‐6 and granulocyte colony‐stimulating factor (G‐CSF), directly promoting tumor growth." (PMID 39429871, 2024). "In the context of OC, the role of IL‐17A producers seems to be complex and dependent on the compartment, species, and tumor stage." (PMID 38566518, 2024). "Conversely, γδ T cell production of IL-17A and VEGF has been linked to angiogenesis, metastasis, and pro-tumor survival." (PMID 38321065, 2024). "In our previous study, IL‐17A was highly expressed in serum and positively correlated with the number of circulating tumor cells, while negatively correlated with disease‐free survival in patients with CRC." (PMID 38491831, 2024).
tumor (continued). "Yet, the recruited γδT cells appear to be influenced by the tumor microenvironment, which can produce IL‐17A or IFN‐γ depending on the tumor stage." (PMID 38273461, 2024). "We also found that macrophages and IL-17A were highly expressed in M. globosa colonization tumor tissues using IF." (PMID 39235230, 2024). "Among patients with MSS CRC, those with lower IL-17A+ cell infiltration have shown better tumor control rates following anti-PD-1 immunotherapy, making IL-17 a potential target." (PMID 39877377, 2024). "This delineated a complex interplay between the gut microbiota, IL‐17A signaling, and the tumor microenvironment." (PMID 38585232, 2024). "Dianzani C and others found that ICOS-Fc treatment inhibited tumor cell migration to the lungs in mice, increasing IL-17A and RAR-related orphan receptor C (RORc) expression while reducing IL-10 and Foxp3 expression." (PMID 39104717, 2024). "The cellular of IL‐17A, particularly T cells and B cells, were identified as playing key roles in tumor growth, with a specific focus on the involvement of IL‐17F." (PMID 38585232, 2024). "Further study manifested that the pro-tumor function of IL17a was exerted by recruiting neutrophils, strongly reflecting neutrophils played a key role in promoting cancer." (PMID 38244071, 2024). "Other studies have also shown that γδ T cells stimulate interleukin-17A (IL-17A) production, which stimulates tumor cell proliferation, induces angiogenesis, and promotes inflammation." (PMID 39595209, 2024). "On the other hand, IL-17A is proved to reduce tumor growth and metastasis, as well as improve prognosis." (PMID 38430256, 2024). "Studies using lung tumor IL-17:KrasG12D murine models have suggested the tumor-promoting role of the IL-17-neutrophil axis, as IL-17A increased the infiltration of neutrophils to the tumor site." (PMID 38983267, 2024). "It is therefore possible that the promotion of tumor cell adhesion of mesothelial cells by IL‐17A+TNF is partly mediated by an enhanced interaction of CD44 with hyaluronan." (PMID 38566518, 2024). "We obtained HGSOC patient tumor tissues and confirmed the elevated expression of IL-17A and IL-17C via reverse transcriptase polymerase chain reaction (qRT-PCR) compared with normal FTE tissues from patients with benign gynecological diseases." (PMID 38255960, 2024). "Given the role of Th17 and Th22 cells in promoting tumor development, IL-17A, IL-17F, and IL-22 are also promising targets in CRC." (PMID 38918278, 2024). "In summary, these data indicate that IL‐17A and TNF cooperatively reprogram mesothelial cells towards a mesenchymal phenotype, resulting in a loss of monolayer integrity and increased tumor cell attachment." (PMID 38566518, 2024). "IL-17A, IL-17F, and IL-22 display anti-tumor effects in CRC, aiding immune cell recruitment, tissue repair, and reducing inflammation and angiogenesis-promoting factors." (PMID 38415252, 2024). "On the other hand, IL-17A stimulates tumor development and progression directly as well as indirectly by inducing secretion of IL-6 by APC." (PMID 38500875, 2024). "Another study confirmed that c-RAF phosphorylation, ERK1/2 and p70 S6 kinase induced by IL-17A and IL-17E were involved in tumor cell proliferation and survival." (PMID 38818476, 2024). "Co-localization of IL-17A and F4/80 macrophages showed that IL-17A was highly expressed in macrophages, which means the IL-17A can recruit macrophages leading to tumor growth." (PMID 39235230, 2024). "Additional studies indicate that the genetic deletion of either IL-17A or IL-17F can also impede tumor development in APCMin tumor mice." (PMID 39906741, 2024). "Although such an increase appeared negligible when correction for multiple comparisons was applied, linear regression analysis revealed that IFNα and IL17A negatively correlated with tumor FKBP51s." (PMID 38651817, 2024).
tumor (continued). "The same tendencies were seen when the association between a number of PD-L1+ lymphocytes distributed in tumour islets and stroma and the IL17A+CD4+-immune phenotype was assessed." (PMID 39409156, 2024). "In OC, the role of IL‐17A producers complex, including both tumor‐promoting and tumor‐suppressive functions, and effecting diverse biological processes." (PMID 38566518, 2024). "For instance, IL-17A can influence Treg function by affecting MDSCs and recruiting MDSCs to tumor sites via the secretion of chemokines CXCL1/2." (PMID 39906741, 2024). "Suppression of the IL‐17A‐IL‐17 receptor signaling pathway decreases the invasive capability of tumor cell lines in vitro." (PMID 38491831, 2024). "This approach allowed us to specifically track the progeny of IL-17A-expressing SFB-specific T cells that migrate from intestinal lamina propria or mesenteric lymph nodes to distal tumor sites." (PMID 39185202, 2024). "In breast tumor-bearing mice, type I IFN directly suppresses the activity of tumor-infiltrating γδ17 T cells, while indirect inhibition of γδ17 T cell-activating factor IL-7 reduces IL-17A secretion through two pathways, thereby impeding tumor progression." (PMID 39253082, 2024). "Moreover, mice bearing HCC tumors showed diminished expression of IL-17A by hepatic type 3 innate lymphoid cells (ILC3s) when they were administered with fecal microbiome from healthy mice or Lactobacillus reuteri, which further implicated delayed tumor growth." (PMID 39120310, 2024). "For example, previous reports show that IL-17A accelerates tumor growth in cervical cancer, probably by stimulating angiogenesis." (PMID 39235230, 2024). "In conclusion, Chandra and colleagues present a comprehensive investigation into the intricate relationship between microbiota, IL‐17A signaling, and tumor growth." (PMID 38585232, 2024). "A significant portion of tumor‐enriched γδ T cells, which generate the proinflammatory cytokine IL‐17A, is defined as γδ T17 cells." (PMID 39429871, 2024). "IL-17A can selectively elevate the expression of chemokines with angiogenic properties by epithelial cells as well as tumor cells, such as CXCL1, CXCL5, CXCL6, and CXCL8." (PMID 38515019, 2024). "In contrast, IL-17F has a tumor suppressive effect in CRC, possibly by inhibiting tumor angiogenesis, and Il17a- and Il17f-deficient mice develop fewer and more tumors, respectively, compared to littermate controls in the AOM/DSS model." (PMID 38500875, 2024). "Previous reports demonstrated that tumor cells treated with IL-17A induce M2 polarization in RAW264.7 and THP-1 cells, possibly as a result of the COX-2/prostaglandin E2 (PGE2) pathway." (PMID 39235230, 2024). "Introduction of Staphylococcus epidermidis into germ-free mice has been demonstrated to restore normal IL-17A production - a chemokine potentially involved in tumor growth and anti-tumor immunity." (PMID 39723372, 2024). "The authors put forward the concept of future clinical trials that combine IL‐17A inhibition with microbial interventions to enhance effectiveness and mitigate the influence of tumor‐promoting microbes." (PMID 38585232, 2024). "The recent study by Chandra and colleagues, published in Cancer Cell, sheds light on the significant impact of microbes, specifically through interleukin‐17A (IL‐17A) signaling, on distant tumor behavior." (PMID 38585232, 2024). "Studies have revealed that among these cytokines, the IL-17 family (IL-17A to IL-17 F) and their receptor (IL-17RA to IL-17RE) are involved in Th17 responses, and they can participate in pro-tumor or anti-tumor responses depending on their phenotype." (PMID 38515019, 2024). "In carcinogenesis, IL-17A has been reported to engage myeloid-derived suppressor cells (MDSCs) that repress anti-tumor activity." (PMID 38816694, 2024). "IL6 produced by cancer-associated fibroblasts (CAF) augmented the production of proinflammatory cytokines such as IFNγ and IL17A by tumor-infiltrating T cells." (PMID 38819641, 2024).
tumor (continued). "RT-qPCR illustrated that IL-17A was notably overexpressed in tumor tissues compared to the adjacent normal tissue." (PMID 38430256, 2024). "Meanwhile, high PD-L1+ lymphocyte infiltration in islets was predominantly found in tumours with high levels of IL-17A+CD4+ T cells in islets and Foxp3+CD4+ T cells in islets and stroma (p = 0.032, p = 0.009 and p = 0.034, respectively)." (PMID 39409156, 2024). "A total of 537 tumour tissue samples were divided into IL17A-hi and IL17A-lo groups (247 patients in each group) based on the median geometric mean expression value." (PMID 37211606, 2023). "We next examined IL-17A effects on the interaction of CD8+ T cells with tumor vascular endothelium by using mouse C166 cells, that carry vascular endothelium characteristics." (PMID 37605139, 2023). "The pro-inflammatory factor interleukin-17A mediates important immune responses in the tumor microenvironment." (PMID 37978543, 2023). "IL-17A is highly expressed in the serum of tumor patients and is closely related to the invasion and metastasis of tumor cells." (PMID 36795736, 2023). "To explore the therapeutic effects of blocking IL-17A in vivo and understand its relationship with immunotherapy, we established a subcutaneous tumor model in mice." (PMID 37978543, 2023). "After tumor removal, during adjuvant treatment, the serum IL-17A level significantly drops, but nevertheless remains elevated compared to the healthy controls." (PMID 37427128, 2023). "In practical application, the paradoxical role of IL-17A in tumour growth and elimination makes a poor match with the "one-size-fits-all" approach." (PMID 37211606, 2023). "For example, SERPINA1 showed close connections to CD8A in CD8+ T cells, CD68 in tumor-associated macrophages, IRF6 in M1 macrophages, NRP1 in DCs, STAT3 and IL17A in Th17 in most digestive cancers." (PMID 37511325, 2023). "Interleukin 17A and IL-17F polymorphisms are associated with increased risk for OSCC and are related to tumor stage and differentiation." (PMID 37373022, 2023). "We suggest that the presence of IL-17A within the tumor microenvironment of NSCLC probably promotes and sustains EGFR activation and ultimately results in tumor proliferation." (PMID 37444399, 2023). "IL-17A in the tumor microenvironment is mainly produced by CD4+ T cells, CD8+ T cells, γδ T cells and various innate immune cell populations." (PMID 37978543, 2023). "IL-17A generally promotes the tumor-promoting activity by affecting the ERK, p38, and NF-κB signaling mechanisms, in an IL-17RA dependent manner." (PMID 37958417, 2023). "In CRC tumor tissue, CHI3L1 is associated with the expression of MMP-8, IL17A, and PD-L1, thereby influencing the tumor microenvironment." (PMID 38003338, 2023). "Stimulation of IL-17A diminishes the stem-like exhausted CTL interaction with tumor endothelium to repress the CTL extravasation and inhibited the CTL self-renewal in the tumor bed." (PMID 37605139, 2023). "For instance, IL-17A has been shown to promote tumor growth by stimulating angiogenesis and invasive capacity of tumor cells along with inhibiting apoptosis." (PMID 36125689, 2023). "And the expression of PD-L1 was significantly reduced in the tumor tissues of the anti-IL-17A mAb and combination treatment groups." (PMID 37978543, 2023). "Our clinical samples suggested a positive correlation between IL-17A and PD-L1 expression in tumor cells." (PMID 37978543, 2023). "Other immune cells with antitumor phenotypes also dramatically decreased in the diseased lungs of C57 mice bearing EO771 tumor after Ifng or Il17a/Il17 genes were knocked out." (PMID 37553342, 2023). "The results showed that IL-17A expression was significantly higher in tumor tissues than in paracancerous tissues." (PMID 37978543, 2023). "Cordycepin can significantly reduce the production of IL-17A in vitro and in vivo, and reduce the expression of its downstream signaling molecules to enhance tumor killing effect and reduce PD-L1 expression." (PMID 37816138, 2023).
tumor (continued). "Chronic IL-17A production, at the protein level, has been shown to support tumor formation and progression." (PMID 37631976, 2023). "It is likely that the host response to MDV infection, which results in IL-17A progression, contributes to tumor formation." (PMID 37631976, 2023). "The IF staining results showed that γδT cells were readily observed in tumour with high IL-17A expression." (PMID 37211606, 2023). "IL-17A is considered to be a prevalent cytokine in the tumor microenvironment and plays a dual role in tumor growth and elimination." (PMID 37978543, 2023). "Studies show that the serum levels of IL-17A were elevated in CRC patients in comparison to healthy individuals or in the circulating tumor cells which also predicted poor survival." (PMID 37176567, 2023). "IL-17A has also been demonstrated to promote tumor angiogenesis through promoting the generation of conventional VEGF or directly acting on the endothelial cells." (PMID 37605139, 2023). "Interleukin-17A (IL-17A) is an inflammatory cytokine, highly expressed in a variety of tumor cells, that can alter the autophagic activity of other cells, thereby causing corresponding lesions." (PMID 36795736, 2023). "In CRC, IL-17A was shown to be involved in tumor progression and angiogenesis by inducing IL-6 through the STAT3 pathway." (PMID 37511431, 2023). "Murine γδ T cells differentiate into either IFN-γ (γδIFN) or IL-17A (γδ) producing effectors early in during thymic development with discrete metabolic programming that influences their responses within tumor microenvironments." (PMID 37063856, 2023). "A study showed that the expression and activation of MMPs are mediated through TNF-α and IL-1 secreted by tumor cells, and IL-17A secreted from the microenvironment plays a role on the regulation of different MMPs." (PMID 36993955, 2023). "Previous cancer studies provide evidence that anti-VEGF resistance is driven by tumor-secreted IL-17A." (PMID 36674854, 2023). "Here, we used scRNAseq with protein validation to provide novel insight into IL-17A–producing γδ T cell subsets in normal and tumor-conditioned lung." (PMID 36480166, 2023). "Since lung Vγ4+ and Vγ6+ cells that produce IL-17A are important mediators of cancer progression and metastasis, we examined the impact of tumor conditioning on these subsets." (PMID 36480166, 2023). "This T cell exhaustion phenotype was corroborated by the significantly lower concentrations of various T-cell associated inflammatory cytokines, such as IFN-γ, TNF-α, IL-6 and IL-17A, in the plasma of tumor-bearing aging mice." (PMID 37752597, 2023). "Consistent with previous findings, we observed that IL-17A was generally elevated in NSCLC tumor tissues and positively correlated with PD-L1 expression." (PMID 37978543, 2023). "Results from our current study indicated that IL-17A stimulation exaggerates tumor vasculature dysfunction to restrain the extraversion of CTLs, particularly the stem-like CTLs, leading to uncontrol of tumor growth." (PMID 37605139, 2023). "IL-17A addition into tumor cell-derived medium significantly reduced the ICAM-1 expression of both murine (C166 cells) and human (HUVECs) vascularly endothelial cells." (PMID 37605139, 2023). "Tumor-infiltrating γδ T cells that express IL-17A promote cancer growth, whereas γδ T cells that express IFN-γ efficiently kill colorectal cancer cells." (PMID 37511431, 2023). "Meanwhile, it is our further work to verify the effect of IL-17A on osteoclast differentiation in vivo by using tumor bone metastasis animal model." (PMID 36795736, 2023). "In contrast to these findings, a previous study highlighted the role of IL-17A-producing γδ TILs in the promotion of tumor progression in patients with CRC, but these results were not confirmed in subsequent studies." (PMID 36793708, 2023).